RSPH10B2 (radial spoke head 10 homolog B2)
Description:
May function as part of the axonemal radial spoke complex 3 (RS3). Radial spoke complexes are important for ciliary motility.
Tractability: Antibody: the Human Protein Atlas places it where antibodies can reach.
Gene: Protein-coding gene on chromosome 7 (6,754,101 to 6,799,365, forward strand). Ensembl gene ENSG00000169402.
Subcellular location: Cytoplasm, cytoskeleton, cilium axoneme; Cell projection, cilium; Cell projection, cilium, flagellum
Subcellular location (Human Protein Atlas): Primary cilium; Cytosol; Microtubules; Plasma membrane
Gene Ontology:
Cellular component: cilium; sperm flagellum; 9+2 motile cilium; axoneme; motile cilium
Genetic constraint (gnomAD): Loss-of-function variants: 6 observed, 13.71 expected, observed/expected ratio (o/e) 0.44, 90% interval 0.24 to 0.86. The synonymous counts are far from expectation, so gnomAD's model fits this gene poorly and the ratio says little. Missense variants: 32 observed, 134.8 expected, observed/expected ratio (o/e) 0.24, 90% interval 0.18 to 0.32. Synonymous variants: 14 observed, 42.76 expected, observed/expected ratio (o/e) 0.33, 90% interval 0.22 to 0.51.
Homologues: Orthologues: mouse Rsph10b (73% identical), rat Rsph10b (73% identical), tropical clawed frog rsph10b (44% identical). Paralogues in human: RSPH10B (99% identical), ALS2CL (15% identical), MORN1 (11% identical), RSPH1 (9% identical), MORN3 (9% identical), SETD7 (7% identical), MORN2 (4% identical).
Diseases named in the same sentence as RSPH10B2 in open-access papers:
RSPH10B2 is named in the same sentence as 1 disease in open-access papers, as found by Europe PMC text mining. Sharing a sentence is not in itself a finding about the gene and the disease. The quoted sentences say what the papers report.
primary ciliary dyskinesia (1 paper, 2025). A rare, genetically heterogeneous, primarily respiratory disorder characterized by chronic upper and lower respiratory tract disease. "The second protein, RSPH10B2, which is present in the cilia and associated with primary ciliary dyskinesia, is primarily expressed in the ciliated cells of the bronchus." (PMID 39417930, 2025).